SAMD9 (sterile alpha motif domain containing 9)
Diseases named in the same sentence as SAMD9 in open-access papers (continued):
Sharing a sentence is not in itself a finding about the gene and the disease.
Myelodysplasia (14 papers, 2017 to 2025). Clonal hematopoietic stem cell disorders characterized by dysplasia (ineffective production) in one or more hematopoietic cell lineages, leading to anemia and cytopenia. "The pathogenic variants in SAMD9 have been associated with bone marrow failure and a predisposition for monosomy 7 myelodysplasia." (PMID 36810551, 2023). "SAMD9 variants are associated with monosomy 7 myelodysplasia and leukemia (M7MLS2)." (PMID 37160314, 2023). "GoF SAMD9 mutations cause MIRAGE (myelodysplasia, infection, restriction of growth, adrenal hypoplasia, genital phenotypes, and enteropathy) disorder, while GoF SAMD9L mutations cause a similar disorder characterized with cytopenia, immunodeficiency, and neurological symptoms." (PMID 29447249, 2018). "SAM domain-containing proteins are implicated in normal and pathologic mechanisms, including SAMHD1 in autoimmunity and SAMD9/SAMD9L in myelodysplasia and myeloid malignancies." (PMID 32241909, 2020). "Mutations in the SAMD9 gene are associated with normophosphatemic familial tumoral calcinosis as well as the MIRAGE (myelodysplasia, infection, restriction of growth, adrenal hypoplasia, genital phenotypes, and enteropathy) syndrome." (PMID 28545555, 2017).
viral infection (11 papers, 2013 to 2024). "A deletion between Msh5 and 1700031A10Rik at the 4th month formed Msh5-1700031A10Rik out-of-frame fusion; Samd9 is a tumor suppressor involving in cell proliferation and innate immune response to viral infection." (PMID 35869059, 2022). "M062 has a known host target, SAMD9, and inhibition of SAMD9 is required for a productive viral infection." (PMID 36103568, 2022). "Samd9l is a Sam domain containing protein with similarities to SAMD9 which has been shown to be important during virus infection and innate immunity." (PMID 25418976, 2014). "MYXV M062 inhibits SAMD9 function, leading to a productive viral infection." (PMID 36103568, 2022). "Two elements had differential expression for all 4 viral infections — MER4_22q12.3 and L1FLnI_7q21.2o — which intersect with the human genes APOL6 and SAMD9, respectively." (PMID 34731091, 2021). "Sterile Alpha Motif Domain-containing 9 (SAMD9) and its close paralogue SAMD9L are two ISGs that were recently shown to play key roles in innate immune responses to viral infection." (PMID 32903701, 2020). "SAMD9 and SAMD9L have also recently been shown to play key roles in the innate immune responses to stimuli such as viral infection." (PMID 23758988, 2013). "In order to figure out whether mRNAs and miRNAs in the ceRNA network have effects on viral infection, we investigated the effect of selected six representative mRNAs (CMPK2, ISG15, PARP10, SAMD9, GBP1, and RIG-I) involved in the ceRNA network upon HTNV infection." (PMID 32232013, 2020). "In particular, 8 genes (Mx1, EPSTI1, XAF1, IFI44L, GBP1, SAMD9, SAMD9L, and CMPK2) were expressed in the highly resistant cell lines HPAF-II and Hs766T but not the highly permissive cell lines MIA PaCa-2 and Capan-1 in the absence of virus infection." (PMID 27533247, 2016).
bone marrow failure (8 papers, 2017 to 2025). "An inherited bone marrow failure panel was sent from peripheral blood and revealed a novel SAMD9 variant (heterozygous c.4460A > G; p.Lys1487Arg) and two heterozygous variants of uncertain significance, TET2 and SBDS." (PMID 37160314, 2023). "Among them, 5 have Fanconi anaemia (71.4% of all bone marrow failure), 1 has SAMD9 deficiency (14.3%), and 1 has DKCA1 deficiency (14.3%)." (PMID 37559153, 2023). "Interestingly, the inherited bone marrow failure molecular panel detected a heterozygous SAMD9 variant of indeterminate significance." (PMID 36810551, 2023). "Chromosome 7 contains the SAMD9 gene loci, and deletion of the antiproliferative SAMD9 GOF mutant results in a clonal selective advantage referred to as revertant mosaicism which mitigates bone marrow failure but precipitates hematologic malignancy." (PMID 41268294, 2025). "An inherited bone marrow failure molecular panel was reported as indeterminate with two heterozygous variants detected in TET2 and SAMD9." (PMID 36810551, 2023). "Very recently, heterozygous gain-of-function mutations in SAMD9 have been reported in 11 patients with IUGR, adrenal insufficiency, and gonadal failure, together with bone marrow failure." (PMID 28346228, 2017).
bone marrow failure syndrome (7 papers, 2017 to 2025). "MDS with monosomy 7 frequently occurs in patients with germline variants in GATA-binding factor 2 (GATA2), sterile alpha motif domain containing 9 (SAMD9), sterile alpha motif domain containing 9 like (SAMD9L), or hereditary bone marrow failure syndrome." (PMID 38203823, 2024). "Inherited bone marrow failure syndromes (IBMFSs) include Fanconi anemia, Diamond–Blackfan anemia, Shwachman–Diamond syndrome, dyskeratosis congenita, severe congenital neutropenia, and other rare entities such as GATA2 deficiency and SAMD9/9L mutations." (PMID 37627314, 2023).
enteropathy (7 papers, 2017 to 2022). "Thus, SAMD9 mutations should be considered as cause of enteropathy in pediatric patients." (PMID 31620126, 2019).
Adrenal insufficiency (6 papers, 2017 to 2024). Insufficient production of steroid hormones (primarily cortisol) by the adrenal glands. "SAMD9-associated variants comprise a wider spectrum of phenotypes than originally reported, including children with neonatal growth restriction and multisystem features but without adrenal insufficiency." (PMID 36060959, 2022).
myeloid neoplasm (6 papers, 2019 to 2025). Proliferation of myeloid cells originating from a primitive stem cell. "SAMD9 is an antiviral factor and tumor suppressor, which is a key factor in the development of congenital immune defense against poxvirus and myeloid tumors." (PMID 40560938, 2025). "SAMD9 and SAMD9L germline mutations have recently emerged as a new class of predispositions to pediatric myeloid neoplasms." (PMID 36074606, 2022). "In addition, SAM domain proteins can be implicated in human pathogenic mechanisms, e.g. SAMD9 and SAMD9L mutations are linked to bone marrow failure that can progress to myeloid malignancies." (PMID 32241909, 2020).
adrenal hypoplasia (5 papers, 2017 to 2023). "Meanwhile, adrenal insufficiency due to adrenal hypoplasia is associated with MIRAGE (myelodysplasia, infection, restriction of growth, adrenal hypoplasia, genital phenotypes, and enteropathy) syndrome due to SAMD9/SAMD9L gene mutations." (PMID 37102642, 2023). "SAMD9 mutation should be considered in patients who present with adrenal hypoplasia and extra-adrenal phenotypes." (PMID 29506479, 2018). "The second group is adrenal hypoplasia, including X-linked adrenal hypoplasia congenita (AHC) caused by NR0B1, adrenal hypoplasia caused by steroidogenic factor-1/NR5A1, IMAGe syndrome caused by CDKN1C and MIRAGE syndrome caused by SAMD9." (PMID 34193132, 2021).
glioma (5 papers, 2017 to 2025). A benign or malignant brain and spinal cord tumor that arises from glial cells (astrocytes, oligodendrocytes, ependymal cells). "SAMD9 was prominently expressed in an immune-suppressive subset of glioma tumor cells and was strongly associated with an interferon (IFN) signature." (PMID 41331572, 2025). "SAMD9 may be a diagnostic or prognostic indicator for low grade glioma and also a new potential therapeutic target for treating gliomas." (PMID 33936093, 2021). "KDR, COL1A2, and SAMD9 were frequently mutated and highly expressed in gliomas with subtype Ims1." (PMID 34815785, 2021). "While SAMD9 has been characterized as a tumor suppressor in lung, breast, and colon cancer, its role in glioma is paradoxical, as it has been reported to drive tumor progression by regulating HOXB8." (PMID 41331572, 2025). "Subsequent IHC analysis on a paraffin-embedded glioma tissue TMA revealed a clear grade-dependent increase in SAMD9 protein levels." (PMID 41331572, 2025). "IHC staining images from the Human Protein Atlas and proteomic data from the UALCAN portal confirmed SAMD9 protein overexpression in glioblastoma relative to normal brain and low-grade gliomas." (PMID 41331572, 2025). "SAMD9 is also under investigation as a potential antigen for mRNA vaccine development, and in low-grade glioma, it correlates with M2-polarized macrophage enrichment, contributing to tumor malignancy." (PMID 41331572, 2025). "Our identification of SAMD9 as an IFN-γ-responsive protein in glioma aligns with its known roles in antitumor and antiviral activities." (PMID 41331572, 2025). "It has been observed that the SAMD9 upregulation triggered an accumulation of macrophages increasing low-grade glioma progression." (PMID 36335405, 2022). "We also detected the expression of SAMD9 in clinical glioma specimens and observed that SAMD9 was indeed increased with tumor grade and increased in high-grade gliomas." (PMID 33936093, 2021). "SAMD9 is significantly up-regulated in glioma, and its expression is positively correlated with tumor grade 39." (PMID 34815785, 2021). "To further explore the role of SAMD9 in the malignant progression of glioma, we analyzed its expression levels in different grades in CGGA dataset 1, TCGA dataset, and CGGA dataset 2 of glioma." (PMID 33936093, 2021). "SAMD9 (Sterile Alpha Motif Domain-Containing Protein 9) was found to be highly expressed in glioma and closely related to histological and genetic features in CGGA and TCGA databases." (PMID 33936093, 2021). "Future research will focus on the exploration of SAMD9 specific inhibitors and evaluating their therapeutic effect in gliomas." (PMID 33936093, 2021). "Among these immune cells, we found that macrophages significantly infiltrated in LGG gliomas and were highly consistent with SAMD9 expression in both CGGA database 1 LGG and TCGA databases LGG." (PMID 33936093, 2021). "Patients with higher SAMD9 expression exhibited shorter OS in Kaplan-Meier analyses in all glioma and LGG (Figure 3Ap < 0.0001; Figure 3Bp < 0.0001)." (PMID 33936093, 2021). "Further analysis of glioma databases revealed that SAMD9 function was closely related to immune responses and SAMD9 enrichment was accompanied by a high M2 phenotype macrophage infiltration." (PMID 33936093, 2021). "SAMD9 expression levels increased along with grade II to III progression very significantly in glioma, it also showed an increasing grade III to IV tendency in the TCGA database." (PMID 33936093, 2021). "The high expression of SAMD9 showed a consistent trend with the typical malignant genetic features disclosing malignancy characters in gliomas." (PMID 33936093, 2021). "SAMD9 expression level was sufficient to predict OS (overall survival) of patients with glioma in three datasets." (PMID 33936093, 2021). "Our previous studies have shown that knocking down SAMD9 in glioma cells decreases glioblastoma progression." (PMID 33936093, 2021).
glioma (continued). "Furthermore, low SAMD9 expression was correlated with Glioma CpG island methylator phenotype (G-CIMP), and significant differences were observed between primary and secondary tumors." (PMID 41331572, 2025). "In the low-grade gliomas (LGGs), the mRNA expression of COL1A2 and SAMD9 was positively associated with the abundance of B cells (COL1A2: r = 0.163; SAMD9: r = 0.506), macrophages (COL1A2: r = 0.333; SAMD9: r = 0.551), and DCs (COL1A2: r = 0.297; SAMD9: r = 0.571) (P < 0.05)." (PMID 34815785, 2021). "The correlation between SAMD9 expression and glioma subtypes could also reflect SAMD9 function attributed to human glioma characteristics." (PMID 33936093, 2021). "In summary, our findings revealed that SAMD9 may serve as a key factor of gliomas immunity and act as an independent prognosis factor." (PMID 33936093, 2021). "In summary, SAMD9 may act as an independent prognostic factor in low-grade gliomas." (PMID 33936093, 2021). "To explore the effects of SAMD9 -on M2 macrophage migrative activity, we stably knocked down SAMD9 expression level in LN229 gliomas cells." (PMID 33936093, 2021). "Diffuse gliomas with high expression of COL1A2, SAMD9, and KDR had poor prognoses in the CGGA cohort (log-rank test, P < 0.05), which was consistent with the TCGA cohort." (PMID 34815785, 2021). "We analyzed SAMD9 expression and its prognostic value across three independent IDH-wildtype glioblastoma cohorts and validated findings via immunohistochemistry in human glioma tissues." (PMID 41331572, 2025). "A better understanding of the role of SAMD9 in LGG and its detailed mechanism could certainly open up a new avenue for anti-glioma therapy." (PMID 33936093, 2021). "However, these compounds failed to significantly downregulate SAMD9-correlated signature in glioma cell lines." (PMID 41331572, 2025). "Till now, the detailed regulatory mechanism of SAMD9 and its impact on tumor immunity in gliomas has not been reported, whether SAMD9 could influence the immune response in gliomas is still unclear." (PMID 33936093, 2021). "We have revealed that knocking down SAMD9 expression levels in glioma cells decreased the glioblastoma cell progression via the AKT/PI3K pathway, but the detailed mechanism of how SAMD9 affected the occurrence of gliomas and its impact on tumor immunity has not been reported in gliomas." (PMID 33936093, 2021).
COVID-19 (4 papers, 2023 to 2025). A disease caused by infection with severe acute respiratory syndrome coronavirus 2. "IPF showed CTSK overexpression in AT2 cells, COPD exhibited NLRP3 activation, and COVID-19 displayed viral defense gene SAMD9 upregulation." (PMID 41122970, 2025). "The differential expression analysis identified six differentially expressed genes (DEGs) shared by myasthenia gravis (MG) and COVID-19, namely SAMD9, PLEK, GZMB, JUNB, NR4A1, and NR1D1." (PMID 38384322, 2023). "In addition, the combination of SAMD9, GZMB, JUNB, and NR4A1 presented excellent diagnostic value in COVID-19." (PMID 38384322, 2023). "In the present study, we identified six shared genes (SAMD9, PLEK, GZMB, JUNB, NR4A1, and NR1D1) of MG and COVID-19 patients through bioinformatic analysis." (PMID 38384322, 2023). "The COVID-19 dataset revealed CAMP (AUC: 0.692), LTF (AUC: 0.764), DEFA1B (AUC: 0.701), SAMD9(AUC: 0.786), GBP1(AUC: 0.757), DDX60 (AUC: 0.802), DEFA4 (AUC: 0.763), and OAS3(AUC: 0.801) that exhibited superior diagnostic capabilities." (PMID 38115996, 2023).
Immunodeficiency (4 papers, 2018 to 2025). Failure of the immune system to protect the body adequately from infection, due to the absence or insufficiency of some component process or substance. "Moreover, mutations in SAMD9 have been linked to immunodeficiency, neutropenia, impaired anti-cytomegalovirus response, and gastrointestinal disorder, and to severe multisystem disorders and complex phenotypes characterized by recurrent infection, dysphagia, and profound deafness." (PMID 36335405, 2022).
neutropenia (4 papers, 2019 to 2025). A decrease in the number of neutrophils found in the blood. "Consistently, the immune defects that we noted in this patient reflected immune cell types demonstrated to express relatively high levels of homeostatic SAMD9, particularly neutrophils, with this patient having developed a single episode of mild transient neutropenia." (PMID 41268294, 2025).
fibromatosis (3 papers, 2007 to 2017). A poorly circumscribed neoplasm arising from the soft tissues. "SAMD9 is expressed at a lower level in a variety of neoplasms associated with β-catenin stabilization, such as aggressive fibromatosis, breast, and colon cancers." (PMID 17407603, 2007). "In the mesenchymal neoplasm, aggressive fibromatosis, subtractive hybridization identified sterile alpha motif domain 9 (SAMD9) as a substantially down regulated gene in neoplasia." (PMID 17407603, 2007). "SAMD9 is expressed at a lower level in aggressive fibromatosis and some cases of breast and colon cancer, while SAMD9L is expressed at a lower level in breast cancer, compared to normal control tissues from the same patients." (PMID 17407603, 2007). "Using primers corresponding to the sequences of the most 5'- and 3'- ends of the SAMD9 gene, a predicted 7 kb transcript was amplified from an aggressive fibromatosis tumor cDNA." (PMID 17407603, 2007). "In addition, SAMD9 expression was dramatically increased in an aggressive fibromatosis tumor with inactivation of the APC gene after transfection of wild type APC." (PMID 19691856, 2009). "SAMD9 and SAMD9L are significantly down-regulated in various neoplasms including aggressive fibromatosis, breast and colon cancers." (PMID 28545555, 2017). "SAMD9 was expressed at a lower level (about 33% the level for normal control tissues) in aggressive fibromatosis (32.22% ± 29.18% vs 100%, p < 0.05 for real-time PCR)." (PMID 17407603, 2007). "For instance, SAMD9 is expressed at lower levels in aggressive fibromatosis, while SAMD9L is not." (PMID 17407603, 2007).
glioblastoma (3 papers, 2021 to 2025). The most malignant astrocytic tumor (WHO grade IV). "Approximately 5% of glioblastoma cases showed SAMD9 amplification or missense mutation." (PMID 41331572, 2025). "Together, these results imply that SAMD9-high glioblastomas establish an immunosuppressive niche via specialized immune constituencies, adaptive stress responses, and ICI resistance mechanisms." (PMID 41331572, 2025). "SAMD9 mRNA expression was significantly upregulated in IDH-wildtype glioblastoma compared to normal brain tissue, as evidenced by TCGA and GTEx data.This upregulation was inversely correlated with reduced promoter methylation." (PMID 41331572, 2025). "Among them, Dasatinib, a multi-target protein tyrosine kinase inhibitor with known efficacy in preclinical glioblastoma models, demonstrated strong binding to SAMD9." (PMID 41331572, 2025). "In summary, our study establishes SAMD9 as a central adaptive mediator in IDH-wildtype glioblastoma, linking hypoxic stress and immune suppression to drive tumor progression and therapy resistance." (PMID 41331572, 2025). "Critically, in a cohort of recurrent glioblastoma patients receiving adjuvant anti-PD-1 therapy, high SAMD9 expression predicted worse clinical outcomes." (PMID 41331572, 2025). "We further investigated the clinical relevance of SAMD9 expression patterns in glioblastoma." (PMID 41331572, 2025). "Furthermore, the prognostic value of SAMD9 was evaluated in three IDH-wildtype glioblastoma datasets (TCGA, CGGA, and Gravendeel)." (PMID 41331572, 2025). "Furthermore, knockdown of SAMD9 attenuated the proliferation, migration and invasion of glioblastoma cells and reduced the activity of the PI3K/AKT signaling pathway." (PMID 33936093, 2021). "Our findings nominate SAMD9 as a promising prognostic biomarker and a potential therapeutic target for IDH-wildtype glioblastoma." (PMID 41331572, 2025). "Yet, the precise regulatory mechanisms of SAMD9 and its impact on tumor immunity in diffuse gliomas, particularly IDH-wildtype glioblastoma, remain elusive." (PMID 41331572, 2025). "SAMD9 emerges as an adaptive response gene to environmental changes, exhibiting a significant immunomodulatory function, which highlights its promise as a therapeutic target for IDH-wildtype glioblastoma." (PMID 41331572, 2025). "Treatment of LN229 glioblastoma cells with CoCl2, a chemical hypoxia inducer that stabilizes HIF-1α/HIF-2α under normoxic conditions, resulted in a dose- and time-dependent increase in SAMD9 protein levels." (PMID 41331572, 2025). "Given SAMD9’s role in antivirus and antitumor responses, and its potential as an IFN-response gene, we sought to comprehensively investigate its expression pattern and clinicopathological significance in IDH-wildtype glioblastoma." (PMID 41331572, 2025).